SUN1 (Sad1 and UNC84 domain containing 1)
Description:
As a component of the LINC (LInker of Nucleoskeleton and Cytoskeleton) complex involved in the connection between the nuclear lamina and the cytoskeleton. The nucleocytoplasmic interactions established by the LINC complex play an important role in the transmission of mechanical forces across the nuclear envelope and in nuclear movement and positioning (By similarity). Required for interkinetic nuclear migration (INM) and essential for nucleokinesis and centrosome-nucleus coupling during radial neuronal migration in the cerebral cortex and during glial migration (By similarity). Involved in telomere attachment to nuclear envelope in the prophase of meiosis implicating a SUN1/2:KASH5 LINC complex in which SUN1 and SUN2 seem to act at least partial redundantly (By similarity). Required for gametogenesis and involved in selective gene expression of coding and non-coding RNAs needed for gametogenesis (By similarity). Helps to define the distribution of nuclear pore complexes (NPCs) (By similarity). Required for efficient localization of SYNE4 in the nuclear envelope (By similarity). May be involved in nuclear remodeling during sperm head formation in spermatogenesis (By similarity). May play a role in DNA repair by suppressing non-homologous end joining repair to facilitate the repair of DNA cross-links.
Synonyms: KIAA0810; UNC84A; FLJ12407
Tractability: Antibody: UniProt predicts a signal peptide or a membrane-spanning region. PROTAC: UniProt records ubiquitination sites on it; ubiquitination databases record sites on it; its protein half-life has been measured.
Gene: Protein-coding gene on chromosome 7 (816,591 to 896,435, forward strand). Ensembl gene ENSG00000164828.
Subcellular location: Nucleus inner membrane
Subcellular location (Human Protein Atlas): Nuclear membrane
Pathways (Reactome):
Reproduction: Meiotic synapsis
Gene Ontology:
Molecular function: cytoskeleton-nuclear membrane anchor activity; identical protein binding; protein binding; lamin binding
Biological process: nuclear matrix anchoring at nuclear membrane; centrosome localization; meiotic attachment of telomere to nuclear envelope; nucleokinesis involved in cell motility in cerebral cortex radial glia guided migration; ossification; response to mechanical stimulus
Cellular component: meiotic nuclear membrane microtubule tethering complex; nuclear envelope; nuclear inner membrane; nuclear membrane; chromosome, telomeric region; cytoplasm; membrane; nucleus
Genetic constraint (gnomAD): Loss-of-function variants: 56 observed, 98.26 expected, observed/expected ratio (o/e) 0.57, 90% interval 0.46 to 0.71. The upper end of that interval is the gene's LOEUF score, 0.71, which puts it in group 2 of 6, group 1 being the genes least tolerant of losing a copy. Missense variants: 1,034 observed, 1,038 expected, observed/expected ratio (o/e) 1, 90% interval 0.95 to 1.05. Synonymous variants: 480 observed, 428.74 expected, observed/expected ratio (o/e) 1.12, 90% interval 1.04 to 1.21.
Homologues: Orthologues: chimpanzee SUN1 (97% identical), macaque SUN1 (92% identical), dog SUN1 (74% identical), guinea pig SUN1 (72% identical), mouse Sun1 (70% identical), rat Sun1 (69% identical), pig SUN1 (60% identical), tropical clawed frog sun1 (47% identical), zebrafish sun1b (42% identical), zebrafish sun1a (13% identical). Paralogues in human: SUN2 (29% identical), SUN3 (15% identical), SPAG4 (15% identical), SUN5 (13% identical).
Diseases named in the same sentence as SUN1 in open-access papers:
SUN1 is named in the same sentence as 43 diseases in open-access papers, as found by Europe PMC text mining. Sharing a sentence is not in itself a finding about the gene and the disease. The quoted sentences say what the papers report.
breast carcinoma (9 papers, 2015 to 2025). "We have previously reported the global loss of the LINC complex components, including SUN1 and nesprin-2, in human breast cancer tissues." (PMID 35663386, 2022). "On the other hand, another study demonstrated that low‐dose X‐irradiations in human breast cancer cells led to up‐regulation of SUN1 expression, which in turn played a central role in the EMT events through the Wnt/β‐catenin signaling pathway." (PMID 39866838, 2025). "Conversely, the invasiveness capacity of breast cancer cells depleted of SUN1 was lower than control cells." (PMID 39866838, 2025). "Immunohistological data showed that SUN1 expression was reduced in breast cancer tissues and cell lines as compared to the normal mammary gland tissues, suggesting that reduction of SUN1 plays a pathological role in breast cancer formation." (PMID 33820871, 2021). "The increased nuclear flexibility of SUN1 + 2 KD carcinoma cells to pass through narrow ECM constrictions combined with their increased motility in 1D make these cells super invaders during mammary tumor invasion." (PMID 34205257, 2021). "Applied to human breast cancer cells, LIV decreased matrix invasion and impaired secretion of osteolytic factors in a SUN1‐ and SUN2‐dependent manner." (PMID 39866838, 2025). "While PDIs tend to be overexpressed in cases of advanced breast cancer, the LINC complex proteins Nesprin-2, SUN1, SUN2, and Lamin A/C are downregulated in human breast cancer cells." (PMID 38891038, 2024). "Analysis of The Cancer Genome Atlas (TCGA) dataset further confirmed that the expression of SUN1 and SUN2 is downregulated in breast cancer compared to normal breast tissue." (PMID 34205257, 2021). "MCF-7 human breast cancer cells were also subjected to LIV, following transfection with control siRNA or siRNA targeting SUN1/2." (PMID 33298883, 2020). "Using immunohistology, we found that a nuclear lamina component, lamin A/C and all of the investigated LINC complex components, SUN1, SUN2, and nesprin-2, were downregulated in human breast cancer tissues." (PMID 26175118, 2015). "In this study we performed immunohistochemistry to demonstrate reduced expression of four LINC complex and nuclear lamina components, SUN1, SUN2, nesprin-2, and lamin A/C, in breast cancer tissues." (PMID 26175118, 2015). "Abnormal regulation of LINC complex genes SUN1, SUN2 and nesprin 2 is also seen in breast cancer." (PMID 32942630, 2020). "Hence, in this study we examined the protein expression levels of a nuclear lamina component, lamin A/C, and three LINC complex components, SUN1, SUN2, and nesprin-2 in breast cancer tissue." (PMID 26175118, 2015). "Furthermore, several cultured breast cancer cell lines expressed less SUN1, SUN2, nesprin-2 mRNA, and lamin A/C compared to noncancerous mammary gland cells." (PMID 26175118, 2015). "We demonstrated significantly reduced expression of SUN1, SUN2, and nesprin-2 proteins in breast cancer (SUN1, 88%; SUN2, 74%; nesprin-2, 79%) regardless of clinicopathological classification and all patients exhibited reduced expression of at least one of four components." (PMID 26175118, 2015).
laminopathies (9 papers, 2011 to 2025). "A previous study found that the accumulation of the inner nuclear envelope protein Sun1 is pathogenic in progeroid and dystrophic laminopathies, which results in AD." (PMID 36982508, 2023). "Abnormal accumulation of INM proteins, such as the integral membrane protein SUN1, has been linked to the pathogenesis of progeric and dystrophic laminopathies in mammals." (PMID 31313624, 2019). "A recent study showed that mis-accumulation of SUN1 underlies the pathology of degenerative features in laminopathies, and concomitantly suggests a gain-of-function versus a loss-of-function model for the action of lamin A mutants." (PMID 22709970, 2012). "Implicating a role for SUN1 in aging, SUN1 overaccumulation is a common finding in mouse models of laminopathies and premature aging (i.e. LMNA-/-, LMNAΔ9)." (PMID 39827403, 2025). "Mps3 is homologous to SUN1, whose accumulation at the INM has been implicated in progeric and dystrophic laminopathies." (PMID 31313624, 2019). "Answering these questions would help to better understand the molecular mechanism through which laminopathies are rescued by SUN1 depletion." (PMID 22709970, 2012). "Lmna N195K csDN-KASH mice demonstrated preserved cardiac function at 10 weeks and 12 weeks of age but still succumbed to early mortality at approximately 17 weeks, in alignment with a previous report of increased lifespan by 5–6 weeks after SUN1 deletion in laminopathy mice." (PMID 41073815, 2025). "Whereas SUN1 and SUN2 have both been reported to interact with lamin A, they appear to have different roles in lamin A mutation-associated laminopathies including Emery–Dreifuss muscular dystrophy (EDMD) and Hutchinson–Gilford progeria syndrome (HGPS), as well as in mammalian development." (PMID 34983624, 2022). "In addition to lamin, nesprin 2 and other LINC proteins, Sun1 and emerin, have been implicated to involve in the pathogenesis of progeria or EDMD of the laminopathies." (PMID 32815283, 2020). "As SUN1 interacts preferentially with prelamin A instead of mature lamin A, it may have a specific role in the processing of lamin A and in laminopathy." (PMID 21655223, 2011). "Given the alterations in lamin A/C location reported in DM1, SUN1 may be increased due to the impossibility of interacting with lamin A/C, mimicking what occurs in mutated lamin A HGPS fibroblasts and thus sharing mechanisms with other laminopathies." (PMID 35008948, 2022).
muscular dystrophy (7 papers, 2014 to 2022). Muscular dystrophy (MD) refers to a group of more than 30 genetic diseases characterized by progressive weakness and degeneration of the skeletal muscles that control movement. "For example, fibroblasts expressing muscular dystrophy-associated variants of SUN1 and SUN2 have significant nuclear mispositioning, and this has also been shown in C2C12 myotubes expressing SUN1 variants." (PMID 32844998, 2020). "Since variants in the SUN proteins have been associated with muscular dystrophies, we sought to identify what other nuclear factors interact with the nucleoplasmic domain of SUN1 in skeletal muscle." (PMID 31686651, 2019). "In this study, we have demonstrated, in several different systems, that muscular dystrophy-associated mutations in SUN1 or SUN2 impair nuclear coupling to the both actin and microtubule networks and disrupt nuclear movement and positioning." (PMID 25210889, 2014). "Our genetic results suggest that mutations or polymorphisms in SUN1 and SUN2 may cause muscular dystrophy and act as modifiers of EDMD and cardiomyopathy." (PMID 25210889, 2014). "However, to date no mutations in SUN1 have been linked to any disease, although some variants have been identified which are associated with muscular dystrophy." (PMID 31686651, 2019).
Hutchinson-Gilford progeria syndrome (5 papers, 2017 to 2023). "Surprisingly, knocking down SUN1 in Hutchinson-Gilford progeria syndrome cells cultured in vitro prevented heterochromatin loss and accelerated senescence; in contrast, an over-accumulation of the SUN1 protein in the NE and the Golgi apparatus triggers nuclear envelope rupture." (PMID 31354529, 2019). "In cells from LMNA-deficient mice, which represent a model for EMDM and the premature aging Hutchinson-Gilford progeria syndrome (HGPS), SUN1 accumulates to abnormal levels." (PMID 28747499, 2017).
progeria (5 papers, 2012 to 2023). "Endothelial cells also accumulate SUN1 in HGPS mouse models, and loss of Sun1 partially rescues progeria phenotypes in mouse models and patient cells." (PMID 36989130, 2023). "SUN1-increased expression has been correlated with accumulation of farnesylated prelamin A in progeria cells." (PMID 22706480, 2012). "We believe that this beneficial effect of Sun1 reduction in progeria cells may be partially due to the regulation of mechanical features of nucleus or cytoskeleton since nuclear lamina network is connected to cytoskeleton by both Sun1 and Sun2 in the LINC complexes." (PMID 32710480, 2020). "Also, we observed that the expression level of Sun2, but not Sun1 or overall level of Lamin A/C, was significantly changed in progeria cells in contrast to WT cells." (PMID 37198162, 2023).
cardiomyopathy (4 papers, 2014 to 2023). A disease of the heart muscle or myocardium proper. "The integral nature of SUN proteins in the LINC complex makes it surprising that compared to other LINC components, relatively few mutations in SUN1 and SUN2 are associated with cardiomyopathy." (PMID 29869195, 2018). "A similar event occurred in myocardial cells in a specific LMNA deletion mice model, which damaged the LINC complex structure caused by knockout or knockdown of SUN1 (a LINC complex protein gene) and in turn, prevented cardiomyopathy progression and extended the lifespan." (PMID 37784143, 2023). "However, the pathology is significantly reduced by deleting Sun1, resulting in cardiomyopathy progression being retarded for at least a year." (PMID 34354059, 2021). "Here the authors show that disruption of the nuclear protein SUN1 in cardiomyocytes, by AAV mediated transduction of a SUN1 inhibitor, significantly suppress cardiomyopathy progression, providing a potential therapeutic route to treat this disease." (PMID 34354059, 2021). "Furthermore, armed with the knowledge that SUN proteins likely play key roles as genetic modifiers, it would be interesting to sequence SUN1 and SUN2 genes in patients with cardiomyopathy in which other LINC complex mutations have been identified that may not fully explain the resulting phenotype." (PMID 29869195, 2018).
cerebellar ataxia (4 papers, 2015 to 2024). A neurological syndrome characterized by clumsy and uncoordinated movement of the limbs, trunk, and cranial muscles. "Sun1 is selectively expressed in Purkinje cells in the cerebellum and Sun1-knockout mice show a marked decrease in cerebellar size, and reduced foliation of the cerebellar cortex, which causes cerebellar ataxia." (PMID 37437070, 2023). "Furthermore, the additional genetic deletion of SUN2 to SUN1 deficiency exacerbates cerebellar ataxia." (PMID 39519078, 2024). "Our findings reveal a cell-type-specific role for Sun1 and Sun2 in nucleokinesis during cerebellar development, and we propose the use of Sun-deficient mice as a model for studying cerebellar ataxia that is associated with mutation of human SYNE genes or loss of Purkinje cells." (PMID 26035387, 2015). "Further, SUN1-knockout mice, which show impaired cerebellar development and cerebellar ataxia, presented altered Golgi morphology in Purkinje cells." (PMID 33686165, 2021). "Conversely, SUN1 knockout mice exhibit cerebellar ataxia; although, no mutations in the SUN1 gene have been identified in SCAR8." (PMID 39519078, 2024).
Emery-Dreifuss muscular dystrophy (4 papers, 2012 to 2022). Emery-Dreifuss muscular dystrophy (EDMD) is characterized by muscular weakness and atrophy, with early joint contractures and cardiomyopathy. "While specific SUN1 and SUN2 alleles have been directly connected to Emery-Dreifuss muscular dystrophy (EDMD) and related myopathies, SUN proteins may also have indirect effects in disorders in which the LMNA gene is mutated." (PMID 28747499, 2017). "For instance, knockdown of SUN1, a semi-redundant component of the LINC complex, rescues Lamin A knockout mice from Emery-Dreifuss muscular dystrophy." (PMID 30477489, 2018).
Infertility (3 papers, 2014 to 2021). "The study of Sun1 knockout male mice evidences a total infertility phenotype due to the disruption of SUN1–telomere interaction required for telomere movement during chromosome recombination in primary SPC." (PMID 33925685, 2021). "Absence of SUN1 provokes defective telomere attachment and causes infertility." (PMID 24586178, 2014). "Although the loss of either SUN1 or SUN2 alone has no overt effect on postnatal growth and longevity, SUN1 null mice are both infertile and deaf." (PMID 34354059, 2021).
glaucoma (2 papers, 2025). Increased pressure in the eyeball due to obstruction of the outflow of aqueous humor. "As a result, ethanolamine kinase 1 (ETNK1), vimentin-type intermediate filament-associated coiled-coil protein (VMAC), nexilin (NEXN), and Sad1 and UNC84 Domain Containing 1 (SUN1) were identified as glaucoma-associated autoantibodies." (PMID 40149693, 2025). "ETNK1, VMAC, NEXN, and SUN1 were identified as glaucoma-associated autoantibodies based on their plasma levels and positive rates." (PMID 41463042, 2025). "In this study, a cohort of cataract, NTG, and POAG patients was examined by CWPA for plasma autoantibodies, and four new autoantibodies, ETNK1, VMAC, NEXN, and SUN1, were detected as glaucoma-related." (PMID 40149693, 2025). "Thus, SUN1 may be involved in the pathogenesis of glaucoma via actin and FAs." (PMID 40149693, 2025).
hearing loss (2 papers, 2021 to 2024). "Instead, KO mice of nesprin-4 or SUN-1 developed progressive hearing loss, as the outer hair cells of the inner ear degenerated and failed to maintain their nuclei in a basal position, concluding that the LINC complex is essential for hearing." (PMID 34685547, 2021). "Mouse models lacking SYNE4 or Sun1 have been shown to exhibit progressive hearing loss associated with DFNB76." (PMID 38525683, 2024).
heart failure (2 papers, 2014 to 2021). Inability of the heart to pump blood at an adequate rate to meet tissue metabolic requirements. "The same CM-specific deletion performed on a Sun1−/− background resulted in a significant increase in longevity to at least 6 months and beyond after birth, revealing that loss of SUN1 significantly extends longevity in mice with Lmna-induced heart failure." (PMID 34354059, 2021). "For example, patient MD-5 from family 5, carrying both LMNA p.R453W and SUN1 p.W377C mutations, developed cardiac disturbances at age 25 and died from heart failure at age 34, which is much earlier than is typical for EDMD patients." (PMID 25210889, 2014). "The absence of SUN1 preserved both EF, FS and GLS (GLS is a separate parameter used to assess myocardial contractility, and is a better predictor of heart failure) in the LmnaF/F:mcm/Sun1−/−mice compared to LmnaF/F:mcm/Sun1+/+ mice." (PMID 34354059, 2021).